PRP4K (pre-mRNA processing factor kinase PRP4K)
Description:
Serine/threonine kinase involved in spliceosomal assembly as well as mitosis and signaling regulation. Connects chromatin mediated regulation of transcription and pre-mRNA splicing. During spliceosomal assembly, interacts with and phosphorylates PRPF6 and PRPF31, components of the U4/U6-U5 tri-small nuclear ribonucleoprotein (snRNP), to facilitate the formation of the spliceosome B complex. Plays a role in regulating transcription and the spindle assembly checkpoint (SAC). Associates with U5 snRNP and NCOR1 deacetylase complexes which may allow a coordination of pre-mRNA splicing with chromatin remodeling events involved in transcriptional regulation. Associates and probably phosphorylates SMARCA4 and NCOR1. Phosphorylates SRSF1. Associates with kinetochores during mitosis and is necessary for recruitment and maintenance of the checkpoint proteins such as MAD1L1 and MAD12L1 at the kinetochores. Phosphorylates and regulates the activity of the transcription factors such as ELK1 and KLF13. Phosphorylates nuclear YAP1 and WWTR1/TAZ which induces nuclear exclusion and regulates Hippo signaling pathway, involved in tissue growth control.
Synonyms: KIAA0536; PRP4; PRP4B; PRP4H; PR4H; PRPF4B; dJ1013A10.1
Tractability: Small molecule: a structure with a bound ligand is known; a high-quality ligand is known; it belongs to a druggable protein family. PROTAC: UniProt records ubiquitination sites on it; ubiquitination databases record sites on it; a small molecule that binds it is known.
Target class: CMGC protein kinase group; Protein Kinase; Enzyme; Kinase
Gene: Protein-coding gene on chromosome 6 (4,021,266 to 4,064,983, forward strand). Ensembl gene ENSG00000112739.
Subcellular location: Nucleus; Chromosome, centromere, kinetochore
Subcellular location (Human Protein Atlas): Nuclear speckles
Pathways (Reactome):
Metabolism of RNA: mRNA Splicing - Major Pathway
Gene Ontology:
Molecular function: protein binding; protein serine/threonine kinase activity; RNA binding; ATP binding; protein kinase activity; protein serine kinase activity
Biological process: positive regulation of hippo signaling; positive regulation of protein export from nucleus; regulation of mitotic cell cycle spindle assembly checkpoint; spliceosomal snRNP assembly; spliceosomal tri-snRNP complex assembly; mRNA splicing, via spliceosome; spliceosome conformational change to release U4 (or U4atac) and U1 (or U11); mRNA cis splicing, via spliceosome; RNA splicing
Cellular component: catalytic step 2 spliceosome; kinetochore; nuclear speck; nucleus; U12-type precatalytic spliceosome; nucleoplasm; chromosome
Genetic constraint (gnomAD): Loss-of-function variants: 13 observed, 96.32 expected, observed/expected ratio (o/e) 0.13, 90% interval 0.087 to 0.22. The upper end of that interval is the gene's LOEUF score, 0.22, which puts it in group 1 of 6, group 1 being the genes least tolerant of losing a copy. Missense variants: 769 observed, 1,201.8 expected, observed/expected ratio (o/e) 0.64, 90% interval 0.6 to 0.68. Synonymous variants: 380 observed, 413.11 expected, observed/expected ratio (o/e) 0.92, 90% interval 0.85 to 1.
Homologues: Orthologues: chimpanzee PRP4K (99% identical), macaque PRP4K (99% identical), guinea pig PRP4K (98% identical), rabbit PRP4K (97% identical), pig PRP4K (96% identical), mouse Prpf4b (95% identical), rat Prpf4b (94% identical), tropical clawed frog prp4k (83% identical), zebrafish prpf4ba (65% identical), Drosophila melanogaster Prp4k (41% identical), Caenorhabditis elegans prpf-4 (34% identical). Paralogues in human: CDK12 (20% identical), CDK13 (18% identical), CDK11B (15% identical), CDK11A (14% identical), CDK17 (14% identical), CDK18 (13% identical), CDK16 (13% identical), CDK14 (11% identical), CDK7 (10% identical), CDK15 (10% identical), CDK3 (10% identical), CDKL5 (9% identical), and 14 more.
Diseases named in the same sentence as PRP4K in open-access papers:
PRP4K is named in the same sentence as 18 diseases in open-access papers, as found by Europe PMC text mining. Sharing a sentence is not in itself a finding about the gene and the disease. The quoted sentences say what the papers report.
triple-negative breast carcinoma (5 papers, 2018 to 2023). An invasive breast carcinoma which is negative for expression of estrogen receptor (ER), progesterone receptor (PR), and human epidermal growth factor receptor 2 (HER2). "For example, trifluridine-induced CIN was shown to impair triple negative breast cancer (TNBC) tumour growth, and at least one study has linked depletion of PRP4K in the MDA-MB-231 xenograft model of TNBC to reduced metastasis in mice." (PMID 35281802, 2022). "The observation that high levels of PRP4K expression correlate with good prognosis of triple-negative breast cancer patients supports a role of PRP4K in tumor suppression." (PMID 29695716, 2018). "Moreover, ovarian and triple negative breast cancer patients harboring tumours with low PRP4K expression exhibit worse overall survival." (PMID 35281802, 2022). "Interestingly, high PRP4K expression levels correlated with good prognosis in triple-negative breast cancer patients, consistent with its role in opposing Yap/Taz activity." (PMID 29695716, 2018). "Furthermore, PRP4K inhibited proliferation and invasiveness of cultured breast cancer cells and its high expression correlated with good prognosis in triple-negative breast cancer patients." (PMID 29695716, 2018). "Interestingly, high PRP4K expression correlates good prognosis in triple-negative breast cancer (TNBC) patients, suggesting that PRP4K may function as a tumor suppressor." (PMID 33869224, 2021).
breast carcinoma (4 papers, 2018 to 2025). "Furthermore, PRP4K inhibits proliferation and invasiveness of cultured breast cancer cells and its high expression correlates with good prognosis in breast cancer patients." (PMID 29695716, 2018). "PRP4K depleted ID8 cells and human MCF7 breast cancer cells also exhibited greater anchorage-independent growth and reduced apoptosis when grown in suspension, consistent with reduced sensitivity to anoikis." (PMID 35281802, 2022).
ovarian carcinoma (2 papers, 2009 to 2022). A malignant neoplasm originating from the surface ovarian epithelium. "When ID8 ovarian cancer cells were transplanted into mice and the surviving fraction of cells was assessed 28 days later, PRP4K expression was greatly reduced, suggesting a survival advantage with PRP4K loss." (PMID 35281802, 2022). "PRP4K protein expression is highly variable in tumour cells from various cancers, and reduced PRP4K expression in breast and ovarian cancer correlates with worse overall survival in several studies." (PMID 35281802, 2022). "This prompted Corkery and others to examine more deeply the relationship between PRP4K gene regulation and taxane resistance in breast and ovarian cancer." (PMID 35281802, 2022). "Thus, reduced PRP4K expression promotes anchorage-independent growth and metastasis in ovarian cancer." (PMID 35281802, 2022). "Since PRP4K protein expression is variable in breast and ovarian cancer, PRP4K may represent a useful predictive biomarker for taxane response, particularly following relapse in ovarian cancer patients treated with taxanes." (PMID 35281802, 2022). "Furthermore, ovarian carcinoma cells isolated from the ascites of a relapsed ovarian cancer patient initially responsive to taxanes, exhibited markedly reduced PRP4K expression compared to the primary tumour and correlated with taxane resistant disease." (PMID 35281802, 2022). "PRP4K is regulated by both the HER2 and estrogen receptor, and its partial loss increases resistance to the taxanes in multiple malignancies including cervical, breast and ovarian cancer." (PMID 35281802, 2022). "The depletion of PRP4K also enhances both Yap and epidermal growth factor receptor (EGFR) signaling, the latter promoting anoikis resistance in breast and ovarian cancer." (PMID 35281802, 2022).
cancer (11 papers, 2018 to 2025). A tumor composed of atypical neoplastic, often pleomorphic cells that invade other tissues. "We will explore the links between PRP4K and cancer in the next sections, beginning with the role of PRP4K in regulating cell division and the cellular response to taxane-based chemotherapy." (PMID 35281802, 2022). "In the next section, we explore more deeply the experimental evidence linking PRP4K regulation to cancer development and therapy responses." (PMID 35281802, 2022). "A few key studies have bridged the gap between PRP4K and its role in cancer by uncovering regulatory functions in cell division, Yap signaling and the cellular response to taxane-based chemotherapy." (PMID 35281802, 2022). "Prp4K is an antioxidant enzyme that protects cells against oxidative damage, and the overexpression of Prp4K conferred resistance to radiation in cancer cells." (PMID 36386215, 2022). "Further study is needed to fully explore the function of PRP4K in cancer progression and how PRP4K is regulated." (PMID 29695716, 2018). "In addition, recent work linking induction of EMT and negative regulation of PRP4K expression provides the first evidence of dynamic regulation of PRP4K gene expression and protein translation during cancer development." (PMID 35281802, 2022). "Despite the growing literature supporting the tumour suppressor role(s) of PRP4K, there are still many mechanistic details missing regarding how PRP4K expression, kinase activity and subcellular localization are regulated, and how low PRP4K expression contributes to cancer development." (PMID 35281802, 2022). "In addition, PRP4K has been revealed to be a haploinsufficient tumour suppressor that promotes aggressive cancer phenotypes when partially depleted." (PMID 35281802, 2022). "Importantly, depletion rather than complete loss of PRP4K expression promotes not only resistance to taxanes but also more aggressive cancer phenotypes including anoikis resistance, increased cell migration and aberrant growth factor signaling." (PMID 35281802, 2022). "Together these data indicate that PRP4K is a key regulator of the SAC and its depletion likely contributes to CIN and aneuploidy, major drivers of cancer development and evolution." (PMID 35281802, 2022). "For example, PRP4K appears to play roles in regulating transcription and the spindle assembly checkpoint (SAC), a key pathway in maintaining chromosomes stability and the response of cancer cells to taxane-based chemotherapy." (PMID 35281802, 2022). "Finally, PRP4K is negatively regulated during epithelial-to-mesenchymal transition (EMT), a process that promotes increased cell motility, drug resistance and cancer metastasis." (PMID 35281802, 2022). "Therefore, while PRP4K regulation of ELK1 demonstrates its role in connecting splicing and transcriptional machinery, there are potential unexplored clinical ramifications of the phosphorylation of ELK1 by PRP4K for both neurodegeneration and cancer." (PMID 35281802, 2022). "PRP4K acts as a key regulator of the SAC during mitosis, and thus its loss alters therapy responses to microtubule targeting chemotherapy and although not experimentally validated, likely also drives CIN during cancer development." (PMID 35281802, 2022). "For example, PRP4K negatively regulates Hippo-Yap signaling through YAP phosphorylation, providing one mechanism by which reduced kinase expression could contribute to increased migration and cancer cell invasion through dysregulation of Yap-target gene expression." (PMID 35281802, 2022). "On the other hand, lentiviral infection of PRP4K but not PRP4KKR into MDA-MB-231 cells increased Yap phosphorylation, reduced Yap target gene expression, and decreased the proliferation and migration of the cancer cells." (PMID 29695716, 2018).
tumor (9 papers, 2007 to 2022). "In particular, to what extent does altered pre-mRNA splicing in PRP4K low tumours contribute to their treatment responses and progression relative to altered phosphorylation of key substrates of this kinase?" (PMID 35281802, 2022). "In the past decade, there have been several studies supporting the notion that the cellular role of PRP4K goes beyond pre-mRNA splicing, and that it has diverse regulatory functions in tumour suppression and chemotherapeutic responses." (PMID 35281802, 2022). "Together these data indicate that PRP4K is a haploinsufficient tumour suppressor in epithelial cancers." (PMID 35281802, 2022). "Thus, as we discuss in this review, PRP4K likely plays evolutionarily conserved roles not only in splicing but in a number of cellular pathways that together contribute to tumour suppression." (PMID 35281802, 2022). "However, over the past decade additional evidence has emerged that PRP4K has many diverse cellular roles beyond splicing that contribute to tumour suppression and chemotherapeutic responses in mammals." (PMID 35281802, 2022). "Therefore, continued research on mechanisms regulating PRP4K expression, substrate specificity and kinase activity, will provide key insights into the cellular roles and tumour suppressor activities of this multi-functional kinase." (PMID 35281802, 2022). "Therefore, in the context of epithelial cancers, PRP4K behaves as a haploinsufficient tumour suppressor whose depletion enhances EGFR signaling and anoikis resistance." (PMID 35281802, 2022). "Like PRP4K, reduced PTEN gene expression is sufficient to promote increased AKT signaling and consequently tumour development." (PMID 35281802, 2022).
PRP4K also shares sentences with these, for which no sentence is quoted: colorectal carcinoma (2 papers); hepatocellular carcinoma (2); infection (2); Alzheimer disease (1); breast tumors (1); colon cancer (1); lung adenocarcinoma (1); lymph node metastasis (1); pancreatic cancer (1); polycystic ovary (1); sarcoma (1); skin cancer (1); virus infection (1).